APOE (apolipoprotein E)
Diseases named in the same sentence as APOE in open-access papers (continued):
Sharing a sentence is not in itself a finding about the gene and the disease.
tumor (continued). "However, whether the adhesion of apoE to HSPG affects these aspects of tumor biology induced by HSPG or not still requires additional investigation." (PMID 32306242, 2020). "The correlation between PanCK and CD14/APOE was −.085/.098, indicating no significant relevance of CD14/APOE with tumour cells." (PMID 39187937, 2024). "PC patients presented a serum lipids difference from non-PC tumor patients in triglyceride (P=0.001), cholesterol (P=0.005), HDL (P<0.001), LDL (P=0.003), apolipoprotein A1 (P=0.001), apolipoprotein B (P=0.007), and apolipoprotein E (P<0.001)." (PMID 34335950, 2021). "Further, in-depth analysis of TCGA-PRAD data revealed significantly higher gene expression profiles for SLC12A2 (P = 0.025), DDAH1 (P < 0.0001), NDRG1 (P = 0.0013), APOE (P < 0.0001), YWHAZ (P = 0.0385), and GDF15 (P < 0.0001), in PCa tumor tissue compared with non-tumoral adjacent tissue." (PMID 33483585, 2021). "Both ABCA1 and APOE were assessed for correlation with NR1H2/LXRB and whilst APOE weakly correlated with NR1H2/LXRB in ER-positive tumours (R = 0.25) it was not correlated in ER-negative tumours; ABCA1 was not correlated with NR1H2/LXRB in either tumour type." (PMID 31683867, 2019). "The suppression of tumour growth in response to TFF2 overexpression in the AOM/DSS model was not, however, significantly altered by knockout of the ApoE gene, suggesting that there may be other important signalling targets beyond ApoE." (PMID 26841680, 2016).
cancer (254 papers, 2007 to 2026). A tumor composed of atypical neoplastic, often pleomorphic cells that invade other tissues. "There would appear to be some clear-cut differences in the levels of evidence in support of the role of APOE in relation to risk between AD and various cancers." (PMID 40149482, 2025). "The PROSPER-derived studies evaluated the relationship between APOE subtypes and cancer risk in the older population." (PMID 39763652, 2024). "Different cancer susceptibility results are caused by the interaction between APOE allele carriers and their genotypes, which has a substantial impact on cancer development and progression." (PMID 39763652, 2024). "In recent years, ApoE has been identified as a potential diagnostic or prognostic marker in many cancers." (PMID 38349474, 2024). "Potential factors that contribute to this relationship include genetic influences such as the apoE phenotype, which affects both cholesterol metabolism and susceptibility to carcinoma." (PMID 39024248, 2024). "For fibroblasts, we recognized five subgroups, including APOE+ cancer-associated fibroblasts (CAFs), APOD+ CAFs, myofibroblastic CAFs (myoCAFs), inflammatory CAFs (iCAFs), and proliferating cells." (PMID 37475874, 2023). "Nonetheless, our results showed that APOE-ε4 was associated with a decreased risk of dying due to cancers in women who were 50 years old and older." (PMID 37434484, 2023). "APOE, known to be implicated in cardiovascular and neurological diseases, is involved in tumorigenesis, cancer cell proliferation, and metastasis, and is associated with amplified oxidative stress." (PMID 38067270, 2023). "In gender-stratified analyses, APOE-ε4 status was associated with a reduced risk for all-cause mortality and mortalities related to cancers in women." (PMID 37434484, 2023). "APOE plays a unique role in AD, and the inverse association between AD and cancer has been previously reported." (PMID 37304007, 2022). "Increased efforts are warranted to assess the role of apoE isoforms in cancer survivors and the mechanisms underlying these apoE isoform-dependent effects." (PMID 36441715, 2022). "ApoE has many functions besides its well-known role in lipid metabolism, which is potentially involved in cancer risk." (PMID 35892323, 2022). "Nevertheless, this is the first study on the relationship between APOE genetic polymorphisms and cancer and CVD in a southern Chinese population." (PMID 36057714, 2022). "A meta-analysis of Mendelian randomization studies has shown an association between the APOE ε2/ε3/ε4 polymorphism and risk of cancer in Asians." (PMID 32998735, 2020). "The association of apoE with BC and how it impacts this carcinoma have been the focus of an increasing number of studies, but the findings still need further development and improvement." (PMID 32306242, 2020). "Previous studies have demonstrated the overexpression of ApoE was associated with a series of malignant behaviors and it was regarded as a prognostic marker in a variety of cancers according to previous studies." (PMID 30631342, 2018). "Consistently, BAPN pre-treatment in ApoE−/− mice caused decreased FAK activation accompanied by diminished cancer cells adhesions." (PMID 29458390, 2018). "Chemotherapy-treated breast cancer patients carrying APOE-4 allele E4, a well-known risk factor for Alzheimer's disease, have a higher risk of cognitive dysfunction during the course of cancer treatment." (PMID 28377717, 2017). "In studies of age-of onset for CAD and cancer risk, such an effect has been demonstrated in the Framingham Heart Study for the APOe-2/3 polymorphism." (PMID 27187494, 2016). "Twenty-five articles that examined the associations of APOE gene ε2/ε3/ε4 polymorphism with either cancer risk (n = 22) or circulating lipid changes (n = 4) were eligible." (PMID 25820350, 2015).
cancer (continued). "Apart from lipid transport apolipoproteins play a wider role in cancers and are known to interact with diverse receptors to elicit cellular events as demonstrated for APOE to cause sustained proliferation and survival of cancer cells." (PMID 25872475, 2015). "For 4 APOE-lipids association studies, data provided in both cancer patients and controls were analyzed separately, resulting in 6 independent studies for TG and 7 studies respectively for TC, HDL-C and LDL-C." (PMID 25820350, 2015). "In the overall cancer group (EH + ECa and ECa), APOE E 2 allele was more frequent among patients compared with controls, but the results were nonsignificant after multiple testing corrections (P = 0.036, PBonferroni > 0.05, OR = 1.54, 95% CI 1.03–2.30)." (PMID 25741405, 2015). "Based on these observations, it is reasonably expected that low circulating HDL-C conferred by APOE gene ε4 allele is causally related with an increased risk of cancer in Asians." (PMID 25820350, 2015). "For 22 APOE-cancer association articles with 26 independent studies, there were 13478 cancer patients and 77592 controls in total." (PMID 25820350, 2015). "We summarized published data on the associations of apolipoprotein E (APOE) gene ε2/ε3/ε4 polymorphism with both cancer risk and circulating lipid profiles, aiming to examine the causal relevance between lipids and cancer risk." (PMID 25820350, 2015). "Age, sex, education, handedness, race/ethnicity, and APOE ε4 allele status were all significantly different between AD/cancer groups." (PMID 25400589, 2014). "However, the mechanism underlying the relationship between ApoE level and cancer development remains elusive." (PMID 40495209, 2025). "Additionally, a recent pan-cancer analysis using data in the public domain revealed that APOE+ TAMs are associated with poor responses to immune checkpoint inhibitors due to their interaction with exhausted CD8 T cells." (PMID 40835684, 2025). "A possible explanation could be that the immunomodulatory effect of APOE ε4 contributes to neuroinflammation and an increased risk of AD,55, 56 but may also infer a protective effect in other circumstances such as cancer." (PMID 40356022, 2025). "Furthermore, as cholesterol has also been closely linked with cancer risk and outcomes and ApoE isoforms have significant effects on cholesterol markers, interrogation into the ApoE isoforms binding interactions with their receptors in cancer is required." (PMID 40149482, 2025). "The M.Sig model using real‐world immunotherapy data accurately predicts the ICI response of pan‐cancer, which may be associated with the interaction between APOE+ macrophages and CD8+ Tex cells." (PMID 38569519, 2024). "The study couldn’t establish a direct causal link between APOE genotype and cancer risk due to the effect of medications on TC levels in patients with vascular disease." (PMID 39763652, 2024). "In clear cell renal cancer, C1Q+TREM2+APOE+ TAMs were associated with cancer recurrence." (PMID 38303024, 2024). "Interactions between APOE genotypes and lipid metabolism may impact cancer risk, though direct causality and population-specific effects remain unclear." (PMID 39763652, 2024). "Recent studies suggest that interactions between lipid metabolism and APOE genotypes may increase cancer risk, particularly for APOE ε2 carriers with low TC levels." (PMID 39763652, 2024). "Likewise, APOE is said to play a role in the activation of several cell pathways associated with cancer progression, including ferroptosis, apoptosis, DNA damage response, and intracellular signaling pathways such as PI3K/AKT, RTK, and TSC/mTOR." (PMID 38067270, 2023). "However, the published data on associations between APOE polymorphism and cancer risk were highly inconsistent." (PMID 36057714, 2022). "The overall mutation rate of APOE was relatively low (less than 1%) across all cancer types." (PMID 37304007, 2022).
cancer (continued). "To further investigate the potential molecular mechanism of APOE involved in the pathogenesis of different cancer types, we analyzed gene alteration and mutation, protein phosphorylation, survival prognosis, GO enrichment, KEGG pathways, and immune infiltration." (PMID 37304007, 2022). "APOE genotype is a potential genetic risk factor for cancer treatment related side effects." (PMID 36441715, 2022). "The study findings suggest that APOE genotype may be associated with presence and severity of cancer treatment-related side effects and symptoms and also influence the response to exercise-based interventions in cancer survivors." (PMID 36441715, 2022). "A meta-analysis revealed that APOE ε4 allele increases the risk of cancer in Asians." (PMID 36057714, 2022). "ApoE is associated with an increased risk of developing various cancers, including the nasopharynx." (PMID 35892323, 2022). "However, recent studies have revealed that ApoE is associated with cancer progression and metastasis." (PMID 31275318, 2019). "APOE is among the best‐verified potential prognostic or diagnostic marker in many other cancers." (PMID 31573738, 2019). "To fill this gap in knowledge and generate added information, we revisited this topic and summarized the associations of APOE gene ε2/ε3/ε4 polymorphism with both cancer risk and circulating lipid profiles in a large meta-analysis implementing Mendelian randomization technique." (PMID 25820350, 2015). "At the requirements of Mendelian randomization technique, causal relevance between circulating lipids and cancer risk was only calculated based on the association between APOE gene ε4 allele and cancer risk in Asians and the relationship between ε3/ε4 genotype and circulating HDL-C reduction." (PMID 25820350, 2015). "Another example of a Mendelian randomisation, originating from Katan’s original hypothesis, used apolipoprotein E (ApoE) genotype to infer causality between cholesterol and cancer." (PMID 24590770, 2014). "ApoE, however, has many other functions beside its well-known role in lipid metabolism, that are potentially involved in cancer risk, as it is involved in tissue repair, inflammatory and immune response, cell growth and angiogenesis, and shows antioxidant properties." (PMID 23098561, 2012). "Despite these interesting findings there remains a significant gap in knowledge as to what might be the mechanisms behind how variation in APOE can mediate these effects and thus be of relevance to the increasing number of reported inverse associations between AD and cancer." (PMID 40149482, 2025). "Taking into account the possibility of tradeoffs in the effects of the APOE polymorphism on the ages at onset of aging-related diseases, it is important to consider applications of the model to data on incidence of such diseases (e.g., cancer and CVD) and cause-specific mortality." (PMID 23682334, 2012). "Subsequently, we analyzed cell‐cell communication and found that the APOE+ macrophage subcluster exhibited extensive communication networks with cancer cells." (PMID 40492378, 2025). "In AD, Aβ-dependent and -independent interactions have been suggested, whereas in cancer, ApoE plays a role in immunoregulation." (PMID 40149482, 2025). "The cancer cells from Apoe-/- mice lacked the effect of the exosomes on their migration ability, and this indicates the importance of ApoE and miRNAs in driving the exosomal transfer by TAMs in the progression of cancer." (PMID 41357196, 2025). "In a study of fall prevention exercise in post-treatment female cancer survivors aged 50–75 years old (ClinicalTrials.gov NCT01635413), the APOE genotype modulated cancer treatment-related side effects and symptoms and response to exercise intervention." (PMID 41465180, 2025). "Recent in-depth studies of ApoE revealed that the expression level of ApoE is upregulated in most cancers and is significantly correlated with the prognosis of patients." (PMID 40495209, 2025).
cancer (continued). "LXR/APOE activation therapy has been explored as a potential target to enhance cancer immunotherapy by modulating innate immune suppression." (PMID 39990672, 2025). "APOE expression also varies among patients based on race, age, cancer stage, nodal metastases and histological subtype." (PMID 39810624, 2025). "Gene expression profiling of macrophages upon exposure to cancer cells in vitro showed that macrophages up-regulate C1Q genes and APOE, as in archetype 4 in vivo." (PMID 41280683, 2025). "Given the special role of APOE+ macrophages in influencing immunotherapy outcomes, as previously highlighted in a pan-cancer analysis 29, we conducted IHC to evaluate APOE expression in both ICB-resistant and ICB-responsive patients." (PMID 40303328, 2025). "Cluster 25 (CD163+ApoE+) macrophages expressed S100A4 and S100A10, while Cluster 18 (ApoE+ki67+) cancer cells expressed high levels of ApoE, Ki-67, and vimentin." (PMID 39695088, 2024). "Subsequently, we selected APOE as a potential therapeutic target and confirmed its differential expression and significant pro-cancer function using in vitro experiments." (PMID 38566155, 2024). "APOE expression varies among tumor types and cancer cell lines, and it has been shown to have prognostic value and influence treatment outcomes in cancers such as lower-grade glioma, kidney renal clear cell carcinoma, and kidney renal papillary cell carcinoma." (PMID 39498386, 2024). "In GC81, exosomal miRNA-21 generated by M2-like TAMs regulates the transfer of phosphatase and tensin homolog (PTEN)/PI3K/Akt signaling between TAMs and cancer cells through the M2-specific apolipoprotein E (ApoE)." (PMID 38341519, 2024). "The association between cancer and MCI remained to be statistically significant after individual adjustment for sex (0.67 [0.48–0.95], p = 0.025), APOE ε4 (0.65 [0.43–0.99], p = 0.046), and smoking (0.68 [0.48–0.98], p = 0.019)." (PMID 38388558, 2024). "Cluster 25 cells (CD163+ApoE+ M2 macrophages) and Cluster 18 (cancer cells) showed the most active cellular interactions." (PMID 39695088, 2024). "Cluster 23 (CD31+ApoE+ EC cells) also exhibited a significant spatial interaction with Cluster 18 cancer cells by S100A10 and Thbs1 secretion." (PMID 39695088, 2024). "On the other hand, a different study suggested that APOE activation was seen to restrict the immune system suppression of cancer cell proliferation, thus promoting cancer growth and metastasis." (PMID 38067270, 2023). "Collectively, these findings underscore the multifaceted role of APOE in different cancer types, contributing to our understanding of its involvement in cancer development, progression, and patient outcomes." (PMID 38054821, 2023). "Recent reports highlight a novel role for the apolipoprotein E (APOE)-TREM-2 axis in cancer, providing promising novel therapeutic targets." (PMID 36161514, 2023). "In order to validate the metabolic and immunosuppressive properties of Macro_APOE/CTSZ in cancer tissues, we used ST data from two CRC patients." (PMID 36587392, 2023). "For example, APOE was shown to suppress metastasis by reducing the invasive behavior of cancer cells, inhibiting endothelial cell recruitment, and enhancing antitumor immunity by modulating myeloid immune cell populations." (PMID 37434484, 2023). "Even though the function of APOE in cancer progression is unclear, it can inhibit proliferation due to its high-affinity interaction with proteoglycan and heparin in the cancer tissue." (PMID 38067270, 2023). "We conducted a comprehensive investigation into the transcriptome profiles of APOE across various cancer types." (PMID 38054821, 2023). "Our findings revealed that APOE exhibited significantly higher expression in several cancer tissues, including stomach adenocarcinoma (STAD)." (PMID 38054821, 2023). "To examine APOE transcriptome level in diverse human cancers, we conducted an analysis using TIMER and Oncomine." (PMID 38054821, 2023).